NF1 (neurofibromin 1)
Diseases named in the same sentence as NF1 in open-access papers (continued):
Sharing a sentence is not in itself a finding about the gene and the disease.
cancer (continued). "Overall, we show the ability of miR-10b to activate the expression of c-Jun through RhoC and NF1, which represents a novel pathway for promoting migration and invasion of human cancer cells." (PMID 27494896, 2016). "Because of the previous diagnosis of NF-1, differentiation from a malignant tumor, such as a malignant peripheral nerve sheath tumor, was necessary." (PMID 27113721, 2016). "For instance, some germline variants in several well-known loss of function cancer driver genes such as DNM2, SMAD4, NF1, PTCH1, PTEN, SMARCB1, TSC1, cause dominant negative Mendelian diseases." (PMID 27080396, 2016). "MEK inhibitors block activity driven by Ras, an oncogene constitutively activated in NF1-associated MPNSTs, while PTT serves as a minimally invasive method to ablate cancer cells." (PMID 27833160, 2016). "As expected, patients with NF1 had an increased frequency of short stature and had been more often diagnosed with cancer when compared to controls." (PMID 26161090, 2015). "Subcutaneous and orthotopic xenograft MPNST models have been generated from both sporadic and NF1 tumors, from established cancer cell lines in all cases." (PMID 25810463, 2015). "These mouse models recapitulate clinical second malignant neoplasm (SMN) induction observed in NF1 individuals, and provide a novel approach for identifying the molecules cooperating in this process." (PMID 26000738, 2015). "In the context of a robust Nf1 mutant mouse model of cancer this work identifies a novel role for an imprinted gene in tumorigenesis." (PMID 26000738, 2015). "This approach identified candidate variants in known cancer genes, including in BCOR, NOTCH2, TET2, NF1, EZH2, and JAK1." (PMID 28721364, 2015). "Since DNA methylation alteration of the TAGLN gene was reported in cancers, we attempted to investigate the TAGLN gene methylation level in the primary NF1-deficient cells." (PMID 25109740, 2014). "With increasing attention in targeting aberrant Ras or its cooperative signaling for cancer treatment, our study provided the information for developing new therapeutic strategies that preferentially kill tumors with Nf1 defect at clinically achievable doses." (PMID 25301738, 2014). "As with IRA2 in yeast, NF1 mutations lead to hyperactive Ras signaling, and are consistent with the high prevalence of somatic NRAS and KRAS mutations in these cancers." (PMID 24386979, 2014). "For this reason, patients with NF1 have four-time greater probability of developing benign and malignant tumors." (PMID 24167749, 2013). "Malignant tumours were reported four times as often in the NF1 group than in the general population." (PMID 16640782, 2006). "To address this question, we now present prospective data concerning the incidence and type of malignant tumours in a cohort of 448 individuals with NF1." (PMID 16786042, 2006). "Firstly, we chose relapse over death to better describe this rare disease, as NF1 patients may develop and die from other malignant tumors." (PMID 40043354, 2025). "Management of both benign and malignant tumors arising in individuals with NF1 is demanding and tumors may be difficult to treat." (PMID 39264447, 2025).
cancer (continued). "Given that loss-of-function in NF1 and RASA1 may lead to increased Ras activity and downstream MEK signaling, we tested small molecule targeting of the RAS-MAPK pathway in sinonasal malignancies." (PMID 40475474, 2025). "Conversely, the HRQoL for physical health of children with NF1 + CI was significantly better than children with cancer, half of whom were receiving medical treatment for their cancer, which may account for this difference." (PMID 40471421, 2025). "This aligns with emerging evidence in other cancers where NF1 loss correlates with MAPK dependency and may inform future strategies for targeted inhibition within NF1-altered CRC." (PMID 40868090, 2025). "In addition to cancers, individuals with NF1 have increased risks for, for example, cardiovascular disease, osteoporosis, scoliosis, dementia, and chronic pain." (PMID 37460655, 2024). "NF1 was neither mutated nor lost in cancer, germline sequencing was negative for an NF1 mutation, and the patient’s karyotype lacked complex aneuploidy typical of MPNST." (PMID 39200173, 2024). "However, the history of a recent cancer explained a large proportion of the reimbursed days of sickness absence with an adjusted estimate of 1.17 for the effect of NF1." (PMID 37460655, 2024). "It is also interesting to note that in the previous experiments generalizing from TCGA to CCLE, we used PIK3CA as an example of a gene where the smallest good model performs best and NF1 as an example where the best model was selected, and this tendency was reversed for these two cancer types." (PMID 39776849, 2024). "Given the close functional links between the MAPK and Hippo pathways in transcription and cancer, we investigated this in NF1 mutant H2052 cells, which displayed MAPK pathway activation." (PMID 39103676, 2024). "SOS1, RASA1, and NF1 mutations were also significantly more often observed in CDX2-suppressed cancers (10.8%, 9.2% and 13.8%, respectively) than in non CDX2-suppressed cancers (1.8%, 1.8%, and 0.9%, Fisher’s exact test p = 0.003, 0.009, and 0.0001, respectively)." (PMID 39452477, 2024). "In Nf1OPG mice, we elucidated a “neuron-immune-cancer cell” circuit, where T cells are induced by Nf1-mutant neuron-produced midkine to express Ccl4, which stimulates TAMs to secrete Ccl5, a key growth factor for Nf1-OPG development and progression." (PMID 38308315, 2024). "However, comprehensive studies on genotype‒phenotype characteristics in Japanese patients with NF1, especially those with malignant tumors, are limited." (PMID 39592598, 2024). "The median age of cancer diagnosis in patients with NF1 is 39 years." (PMID 36684394, 2023). "The ΔS technique used here, in tandem with a supplemental ΔS web tool, simplifies HTS analysis and may provide a springboard for further investigations into drug response in NF1-related cancers." (PMID 38136356, 2023). "Therefore, NF1-mutated cells demonstrate hyperactivation of the Ras/mitogen-activated protein kinase (MAPK) signaling pathway, a major driver of cancer." (PMID 37627552, 2023). "Consequently, recent studies explore drug combinations that exploit the oxidative unbalance of cancer cells to further increase ROS as innovative therapeutic approaches, specifically in NF1-altered cancers." (PMID 37627552, 2023). "Although, to date, PDT has not been selectively approved as a treatment for cancer associated with NF1, some studies have demonstrated promising results with different sensitizers, in some cases also associated with systemic drugs." (PMID 37627552, 2023).
cancer (continued). "The use of S indices, particularly ΔS mean when data are available for multiple cell lines with a common reference line, can be useful in the high-throughput screening assessment of potentially therapeutical useful compounds for the treatment of NF1-related tumors and other cancers." (PMID 38136356, 2023). "CDKN2A, IKZF1, ETV6, RUNX1, and FLT3 were the top genes mutated in leukemias, while somatic alterations in ALK, NF1, and PTEN primarily occurred in solid tumors, suggesting that the driver alterations are either common to cancer (e.g., cell cycle) or specific to pediatric cancer histotype." (PMID 36845394, 2023). "Notably, innovative therapeutic approaches explore drug combinations that further increase reactive oxygen species to boost the oxidative unbalance of NF1-altered cancer cells." (PMID 37627552, 2023). "The remaining most frequent mutated cancer driver genes found in early-stage samples (KMT2C, ALK, BRCA2, GRM, ATM, and BRCA1) were not among those found to be the most frequently shared in late-stage samples (MUC16, CSMD3, KNT2C, NF1, LRP1B, SPEN, and TRRAP)." (PMID 37446001, 2023). "As FCN-159 is a MEK inhibitor, it is hoped that these results may contribute to the understanding of treatment to numerous cancers, not only NF-1-related malignancies." (PMID 37400844, 2023). "In addition, some NF1-related cancers have been demonstrated to be sensitive to the toxic activity mediated by ROS." (PMID 37627552, 2023). "Although sporadic NF1 mutations are frequently observed in human cancers, individuals with NF1 are born with one mutated (non-functional) copy of the NF1 gene (germline NF1 gene mutation)." (PMID 35188187, 2022). "Our data indicate that the combination of NF1 mutation and PTPN11 mutation drives the malignancy of NF1 cells and that SHP-2 inhibition by BRAP is a potential therapeutic strategy for NF1-associated malignant tumors." (PMID 35625983, 2022). "Their presence should raise suspicions of a potential diagnosis of CMMRD in young cancer patients or patients with suspected NF1 but without an NF1 or SPRED1 pathogenic variant." (PMID 35158896, 2022). "The NF1 gene spans approximately 280kb of genomic DNA, which is composed of 57 constitutive exons and 4 alternate splicing exons (9a, 10a2, 23a, and 48a), serving as a cancer suppressor gene." (PMID 36620543, 2022). "Lastly, the mutations of NF1 or TSC genes, whose biological function directly impacts DNA damage signaling and repair and cell cycle checkpoint arrest controls, have been associated with cancer and radiosensitivity." (PMID 36551628, 2022). "Thus, NF1 loss-of-function mutations lead to hyperactivated RAS, whose downstream effects contribute to the elevated cancer risk in NF1 patients." (PMID 34464388, 2021). "This aspect of our model suggests that among the risks faced by individuals with NF1, progression of benign irradiated disease may represent a greater hazard than induction of a normal-tissue-derived secondary cancer." (PMID 34131650, 2021). "Emphasizing on the potential role of Nf1 loss in resistance to BRAF and EGFR inhibitors, they also suggested this could be a potential strategy for other cancer types with related changes to the NF1-FAK1 pathway." (PMID 34781949, 2021).
cancer (continued). "We then performed MTT assays and clonogenic cell survival assays to further confirm whether loss of NF1 and DUSP9 causes lenvatinib resistance in cancer cells." (PMID 34795217, 2021). "Inhibiting MEK could reinstate AIS in cancers with deregulated PI3K/AKT/mTORC1 signaling and NF1 loss." (PMID 31285545, 2020). "The great involvement of this gene in different cancers and its differential expression patterns in NF1-enriched tissues may indicate that the occurrence of minor variants in this gene could act as phenotype modifiers in NF1." (PMID 32858845, 2020). "The mechanisms that regulate adaptive kinome reprogramming in NF1-deficient cancers are not well-elucidated." (PMID 32245042, 2020). "In another in vitro drug screening effort, seven NF1-associated human MPNST and one sporadic MPNST cell line were used in a medium throughput screen of 130 drugs predicted to be useful for NF1-associated cancer therapy based on an analysis of the literature." (PMID 32353955, 2020). "While the majority of Class 1 (RAF dependent) MAP2K1 mutations are associated with co-mutation in BRAF, NRAS, or NF1, only a small proportion of class 2 (RAF regulated) cases and no class 3 (RAF regulated) cases share these co-mutations in a limited pan-cancer analysis." (PMID 32483240, 2020). "In cluster II PPGLs with loss-of-function mutations in NF1 gene, the trend for a relatively high COX-2 immunoreactivity is consistent with another report on elevated COX-2 and prostaglandin E2 (PGE2) levels in NF1 malignant peripheral nerve sheath tumors." (PMID 31142060, 2019). "The glutamate dependence of LUAD tumors harboring mutations to Nf1 and their susceptibility to PSAT1 inhibition may potentially be extended to additional cancers with alterations in the NF1–FAK1 pathway." (PMID 31036704, 2019). "For patients with NF1, benign and/or malignant tumours are often combined." (PMID 31805970, 2019). "Because proteins encoded by mutated genes in inherited genetic disorders are likely to interact with proteins known to cause similar disorders, suggesting the existence of disease PPI subnetworks, we further analyzed the correlations between cancer cases and NF1 PPIs." (PMID 31466283, 2019). "To assess whether our filtering strategy retained known somatic mutations, we tested the impact of this strategy on the hotspot mutations in five known cancer-associated genes: BRAF, RAS family (HRAS, NRAS, and KRAS), and stop-gain NF1 gene mutations." (PMID 30662871, 2018). "Recently, the advent of next generation sequencing revealed a high mutation frequency for the NF1 gene in a number of sporadic cancers that are not typically associated with NF1 patients." (PMID 30479396, 2018). "Benign and malignant neoplasms may arise in the abdomen in both paediatric and adult patients with NF1." (PMID 30187267, 2018). "Whereas NF1 and NF2 guarantee the formation of especially multiple benign tumors (including non-diffuse gliomas) in a lifetime, Li–Fraumeni patients pose a greater risk to developing a malignant tumor, including a diffuse glioma." (PMID 29616301, 2018). "However, most of the tumors from the Nf1+/+ mice did progress to frank malignant carcinoma lesions (Fischer exact test value = 0.015)." (PMID 30479396, 2018). "Therefore, we systematically evaluated the expression of NF1 in normal and cancer GC tissues and investigated its prognostic relevance in GC." (PMID 29137312, 2017).
cancer (continued). "Also, loss of NF1gene lead to epithelial-mesenchymal transition (EMT), thereby implicating NF1 in tumorigenesis and cancer metastasis." (PMID 29137312, 2017). "In the lung adenocarcinoma TCGA, NF1 mutations were found to be significantly represented in cancers not harbouring abnormalities of RAS, RAF or receptor tyrosine kinases." (PMID 26410619, 2015). "Hence, NF1 loss phenocopies KRAS mutation and patients with such cancers can also be considered a suitable molecular cohort to treat with the selumetinib/docetaxel combination, which has proven benefits in KRAS mutant disease." (PMID 26410619, 2015). "Apart from the development of malignant tumors in the Nf1 mutant mouse background, genetic modifiers may hold broader relevance for the NF1 mutant phenotype in humans." (PMID 26000738, 2015). "To rule out NF1 mosaicism, we performed targeted resequencing (Ion AmpliseqTM Comprehensive Cancer Panel, Life technologies®) of NF1 genes using DNA extracted from formalin-fixed paraffin-embedded tissues of the lesion, and found no disease-causing mutation in NF1 gene of the lesion." (PMID 26444007, 2015). "Such evidence may shed some light on cancers thought to be principally driven by MAPK activation, but nevertheless, the discovery of NF-1 signaled the dawn of a new era for NF-1 associated tumors with hyperactive RAS signaling and RAF activation." (PMID 26525348, 2015). "However, there is no report correlating the presence of gene duplication with the presence of malignant neoplasms in NF1 patients, as we can see in this case." (PMID 25580325, 2014). "Duplications are rare and phenotype in patients bearing duplication of NF1 gene is thought to be restricted to developmental abnormalities, with no reference to cancer susceptibility in these patients." (PMID 25580325, 2014). "With the exception of a few hereditary susceptibility genes, such as NF1 and NF2, drivers for this cancer type remain largely unknown." (PMID 24009526, 2013). "The genetic mechanism of carcinoma development in patients with NF1 is not well understood." (PMID 24137429, 2013). "However, the genetic mechanism of carcinoma development in patients with NF1 is not well understood." (PMID 24137429, 2013). "Seminog and Goldacre recently analyzed 697 cases of carcinomas in 6,739 patients with NF1." (PMID 24137429, 2013). "Appreciation of the existence of molecular heterogeneity in NF1-associated tumors is important not only for optimizing somatic mutation detection, but also for understanding the mechanisms of NF1 tumorigenesis, a prerequisite for the development of specifically targeted cancer therapeutics." (PMID 23244685, 2012). "For the leading causes of NF1-associated deaths, we found an excess for malignant neoplasms of connective and other soft tissue and brain, which is not surprising." (PMID 21439034, 2011). "In all these lesions, NF1, as a recessive cancer gene, exhibits a second mutation, not infrequently as the sole detected somatic driver event, consistent with Knudson’s two-hit hypothesis." (PMID 40000831, 2025). "Germline NF1 variants leading to RAS activation and MAPK pathway activation increase the risk of BC, especially in women under 50 years of age, which may lead to an increased risk of cancer mortality." (PMID 40941673, 2025). "Additionally, although the NF1 gene is located on the long arm of chromosome 17 (17q11.2), no mutations in this chromosome were detected in the cancer gene panel test." (PMID 39497595, 2024).